RNU6-1128P (RNA, U6 small nuclear 1128, pseudogene)
Gene: Small nuclear RNA gene on chromosome 22 (31,222,745 to 31,222,853, reverse strand). Ensembl gene ENSG00000199695.
Homologues: Orthologues: chimpanzee U6 (98% identical), macaque U6 (86% identical), dog U6 (72% identical), rat U6 (72% identical), dog U6 (70% identical), guinea pig U6 (67% identical). Paralogues in human: RNU6-43P (81% identical), RNU6-1243P (80% identical), RNU6-24P (80% identical), RNU6-116P (79% identical), RNU6-140P (79% identical), RNU6-25P (79% identical), RNU6-33P (79% identical), RNU6-378P (79% identical), RNU6-727P (79% identical), RNU6-1 (78% identical), RNU6-1060P (78% identical), RNU6-11P (78% identical), and 1287 more.